U6 (U6 spliceosomal RNA )
Synonyms: LOC124900885
Gene: Small nuclear RNA gene on chromosome 4 (29,510,635 to 29,510,737, forward strand). Ensembl gene ENSG00000283666.
Gene Ontology:
Molecular function: U4 snRNA binding
Biological process: formation of quadruple SL/U4/U5/U6 snRNP; spliceosomal tri-snRNP complex assembly
Cellular component: U4/U6 x U5 tri-snRNP complex; U6 snRNP
Homologues: Orthologues: chimpanzee U6 (97% identical), macaque U6 (84% identical), dog U6 (81% identical), guinea pig U6 (80% identical), rabbit U6 (74% identical). Paralogues in human: RNU6-411P (84% identical), RNU6-1081P (83% identical), RNU6-1145P (83% identical), RNU6-1316P (83% identical), RNU6-35P (83% identical), RNU6-38P (83% identical), RNU6-393P (83% identical), RNU6-639P (83% identical), RNU6-1067P (82% identical), RNU6-74P (82% identical), RNU6-10P (81% identical), RNU6-151P (81% identical), and 1287 more.